EGFR (epidermal growth factor receptor)
Diseases named in the same sentence as EGFR in open-access papers (continued):
Sharing a sentence is not in itself a finding about the gene and the disease.
ameloblastoma (continued). "A recent published paper about EGFR signaling in immortalized ameloblastoma cell culture shows convincing images of EGFR nuclear localization, however, the authors do not mention this important feature." (PMID 25991665, 2015). "Previous studies in the literature evaluated EGFR expression in ameloblastomas, and their results were divergent." (PMID 22300665, 2012). "Ameloblastoma is a tumor originating from EGFR-expressing odontogenic epithelium, with expression levels ranging from 0% to 100% in some studies." (PMID 21968082, 2011). "Ex vivo the presence of ameloblastoma tumor and expression of EGFR was confirmed in each AB PDX." (PMID 36357495, 2022). "We hypothesize that expression of EGFR in ameloblastomas may be used to specifically visualize tumors." (PMID 36357495, 2022). "Several studies demonstrated a strong EGFR expression in ameloblastomas." (PMID 25991665, 2015). "Inhibition of EGFR was suggested as a treatment option for a subset of ameloblastomas." (PMID 25991665, 2015). "In this sense, molecular targeted therapy may be useful in aggressive and recurrent cases and in vitro experiments pointed to anti-EGFR therapy as an option for the treatment of a subset of BRAF wild-type ameloblastomas." (PMID 25991665, 2015). "Since ameloblastomas are EGFR-positive tumors, anti-EGFR agents could be considered to reduce the size of large tumors and to treat unresectable tumors that are in close proximity to vital structures." (PMID 22300665, 2012). "In addition, nuclear EGFR colocalized with Cyclin D1 in ameloblastomas." (PMID 25991665, 2015). "Radiolabeled anti-EGFR demonstrates specificity for ameloblastoma PDX tumor xenografts, we believe 89Zr-panitumumab is an attractive target for pre-surgical imaging of ameloblastomas." (PMID 36357495, 2022). "EGFR functions downstream of EGF and stimulates the migration and invasion of human ameloblastoma in an MMP-9 dependent mechanism." (PMID 29029486, 2017). "This study was carried out to elucidate the relationship between the expression of EGFR, CD10 and Ki-67 labelled index and ameloblastoma recurrence using clinical and pathological data." (PMID 22300665, 2012). "So, the aim of the present study is evaluation of EGFR, CD10 expression and Ki-67 labelled index in ameloblastoma and their relation to recurrence." (PMID 22300665, 2012). "Using EGFR as a biomarker for ameloblastoma would allow for the differentiation of tumor compared to normal tissue." (PMID 36357495, 2022). "In addition, as in cell culture anti-EGFR treatment was proved effective for a subset of ameloblastomas (i.e. those BRAF wild-type), our findings bring to light a possible resistance mechanism to anti-EGFR therapy in such tumors, as shown for other neoplasms." (PMID 25991665, 2015). "Studying the role played by EGFR, CD10 and Ki67 in the recurrence of ameloblastoma." (PMID 22300665, 2012). "In the current study, all ameloblastomas exhibited EGFR immunoexpression with no identified relation to recurrence." (PMID 22300665, 2012). "The nuclear localization of EGFR has not been previously explored in ameloblastomas." (PMID 25991665, 2015). "In primary ameloblastoma cells, treatment with EGFR monoclonal antibodies (cetuximab and panitumumab) or EGFR tyrosine kinase inhibitors (erlotinib, gefitinib and AG1478) suppressed cell growth, suggesting these therapies are effective for the treatment of a subset of ameloblastomas." (PMID 25991665, 2015). "Our data demonstrated that CD10-positive tumors with high Ki67 index were associated with high recurrence rate, while EGFR expression was not predictive for prognosis in ameloblastomas but may render such tumors candidate for the new targeted anti-EGFR treatment modalities." (PMID 22300665, 2012). "Furthermore, all cases of ameloblastoma and dentigerous cysts, but no OKC samples, were positively stained for EGFR." (PMID 33374329, 2020).
Cognitive impairment (18 papers, 2014 to 2026). Abnormal cognition is characterized by deficits in thinking, reasoning, or remembering. "Another gene that was upregulated in AD and HD PCs that is also associated with cognitive impairment was the gene encoding epidermal growth factor receptor (EGFR), an interacting partner of many other detected DEGs." (PMID 39807599, 2025). "Leukoencephalopathy and cognitive impairment were primary late toxicities in present study, and only history of EGFR-TKI treatment was a risk factor for grade 2 leukoencephalopathy in multivariate analysis, which had not been reported by other studies." (PMID 24884773, 2014). "Collectively, these results suggest that administration of the EGFR inhibitor erlotinib improves tau-mediated cognitive impairments in PS19 mice by increasing hippocampal spinogenesis." (PMID 39434878, 2024). "Recently, an EGFR pathway-regulating compound (yhhu-3792) was reported to induce cognitive impairment in mice by inhibiting neural pathways in the hippocampus." (PMID 33489880, 2020). "Patients received EGFR-TKI treatment had higher incidence of grades 2–3 cognitive impairment with grade 2 leukoencephalopathy." (PMID 24884773, 2014). "CURCUMIN, a drug that interacts with EGFR, is used to treat mild cognitive impairment." (PMID 39273172, 2024). "Nevertheless, the correlations between the RhoA/ROCK1 and EGFR/PI3K/Akt signaling pathways and the key factors involved in the occurrence of surgery-induced cognitive impairment need further experimental verification." (PMID 39781463, 2025). "Third, the cognitive impairment induced by ketamine was reversed by PROG and ALLO add-on treatments, and the PGRMC1/EGFR/GLP-1R/PI3K/Akt pathway was upregulated." (PMID 33767621, 2021). "However, in patients with asymptomatic brain metastasis, the combined EGFR TKI and radiotherapy treatment and EGFR-TKI-only treatment achieved similar iPFS, but the former may result in memory or cognition impairment months later." (PMID 36612183, 2022).
ependymoma (18 papers, 2011 to 2025). A WHO grade II, slow growing tumor of children and young adults, usually located intraventricularly. "Lapatinib, an epidermal growth factor receptor inhibitor, was used because of its ability to inhibit both ErbB2 (human epidermal growth factor receptor 2) and ErbB1 (epidermal growth factor receptor), which are frequently overexpressed in ependymomas." (PMID 34885237, 2021). "In ependymoma EGFR upregulation, a target of monoclonal antibodies and small molecule inhibitors, correlated with ARG2 (FDR 0.000)." (PMID 28969007, 2017). "The rationale for combining TMZ with lapatinib relied on the fact that this treatment targets the epidermal growth factor receptor (ErbB1) and the related family member human epidermal growth factor receptor 2/neu (ErbB2), which are both overexpressed on ependymoma tumor cells." (PMID 39199553, 2024). "Lapatinib targets the epidermal growth factor receptors (ErbB1 and ErbB2), which may be expressed by ependymoma cells." (PMID 35384591, 2022). "In addition, ependymomas have shown frequent gain and amplification of the EGFR gene located at 7p11.2, as an independent prognostic factor for poor survival." (PMID 22053178, 2011). "Moreover, besides unique mutational profiles of H3F3B p.K27I-mutant DMGs, DNA methylation analysis showed H3F3B p.K27I-mutant DMGs formed a cluster separate from all other entities with H3K27me3 loss including H3K27M mutant DMGs, EGFR-altered DMGs and posterior fossa group A (PFA) ependymoma." (PMID 40849656, 2025). "Nonetheless, the role of protein kinase signaling has been implied in ependymoma tumorigenesis, prompting several ongoing studies evaluating TKIs targeting RET, ALK, ROS, IGFR, PDGFR, FGFR, or EGFR, as well as inhibitors targeting PI3K, mTOR, KIT, and CDK4." (PMID 40238025, 2025). "However, our combined approach identified novel potential biomarker candidates in ependymoma with a known relationship to cancer: ERRB2, EGFR, TWIST1, CDK4, HDAC9, and ARHGEF5 genes." (PMID 26185765, 2015). "The authors identified eight new ependymoma oncogenes and ten new ependymoma TSGs, which converged on dysregulation of specific cell functions, including trafficking of growth factor receptors, FGFR and EGFR, known to be oncogenic in ependymoma." (PMID 26682265, 2015). "Interestingly, none of the 16 ependymoma samples contained alterations in the EGFR-MAPK pathway; this is consistent with the idea that tumorigenesis is driven by entirely different mechanisms in different cell types within the developing central nervous system." (PMID 23592488, 2013).
Hepatic steatosis (18 papers, 2012 to 2026). Steatosis is a term used to denote lipid accumulation within hepatocytes. "We found in different mouse models that hepatic steatosis is associated both with a downregulation of GH pathway and a downregulation of EGFR expression (personal data)." (PMID 23050157, 2012). "We therefore hypothesize that the loss of liver proliferation capacity in liver steatosis is related to the GH/EGFR axis misregulation." (PMID 23050157, 2012). "Restoration of EGFR reversed the downregulation of the PI3K-mTORC1 signaling pathway, thereby alleviating metabolic-associated fatty liver disease and hyperlipidemia phenotypes." (PMID 40312430, 2025). "Lycorine ameliorated hepatic steatosis, oxidative stress and ferroptosis by affecting the EGFR/PI3K/AKT signaling pathway in MASLD mice." (PMID 39604837, 2024). "Altogether, these data revealed that EGFR signaling regulates hepatic steatosis via the MEK/ERK cascade." (PMID 35886933, 2022). "Subsequent mechanistic investigation revealed that lycorine alleviated hepatic steatosis, oxidative stress, and ferroptosis through suppression of phosphorylated epidermal growth factor receptor (EGFR) expression, leading to inhibition of the PI3K/AKT signaling pathway." (PMID 41601875, 2026). "Conversely, restoration of EGFR ameliorated the metabolic-associated fatty liver disease and hyperlipidemia phenotypes without affecting blood glucose levels." (PMID 40312430, 2025). "To verify whether CAV1 prevents APAP-aggravated hepatic steatosis by suppressing Ang II/EGFR/ERK signaling and promoting autophagy, we applied two inhibitors to L02 cells." (PMID 35886933, 2022). "In mouse models on a HFD, NDL PCBs, e.g. Aroclor 1260, increased diet-induced hepatic steatosis, inflammation and fibrosis by affecting pathways regulated by epidermal growth factor receptor, constitutive androstane receptor (CAR, Nr1i3) and Pregnane X receptor (PXR, Nr1i2)." (PMID 34548932, 2021). "In animal studies, EGFR may play a vital role in lipid metabolism in adult male mice, and EGFR inhibitors had effects on reducing serum lipid levels and hepatic steatosis in high-fat-diet-induced obese mice." (PMID 34564376, 2021). "According to the current results, EGFR signaling may be a novel target for the treatment of hepatic steatosis and steatohepatitis, which are the early stages of NAFLD." (PMID 30735525, 2019). "Moreover, EGFR inhibition using PD153035 induced a significant improvement in hepatic steatosis, which was accompanied by improved intrahepatic lipid levels." (PMID 30735525, 2019). "Apart from its role in inflammation, prostasin may also amplify phosphorylation of extracellular signal-regulated kinase through the prostasin/epidermal growth factor receptor/extracellular signal-regulated kinase axis in the liver, thus improving glucose tolerance and hepatic steatosis." (PMID 35922613, 2022). "Conversely, EGFR inhibition decreased liver de novo lipogenesis, leading to improvements in HFD-induced hepatic steatosis and glucose intolerance." (PMID 39937764, 2025). "Lycorine ameliorated hepatic steatosis, oxidative stress and ferroptosis in MASLD mice by inhibiting the expression of phosphorylated EGFR, inhibiting the PI3K/AKT signaling pathway." (PMID 39604837, 2024). "Exosomes from R patients, those exhibiting a clinical improvement of liver steatosis, were found to decrease α-SMA, COL1A1, Vimentin, and EGFR expressions by LX-2 cells (stellate cells), leading to a decrease in the extracellular matrix (ECM) protein deposition and fibrosis." (PMID 38338770, 2024). "Lycorine could ameliorate hepatic steatosis, OS and ferroptosis in MASLD mice by inhibiting the expression of phosphorylated EGFR, which in turn inhibited the PI3K/AKT signaling pathway." (PMID 39604837, 2024).
Hepatic steatosis (continued). "The study then explored the relationship between the phosphorylation of EGFR and ERK1/2 (the downstream of Ang II) and the aggravation of liver injury in alcoholic fatty liver induced by APAP, and this is the first study to link this disease model with Ang II/EGFR/ERK signaling pathways." (PMID 35886933, 2022).
hypopharyngeal carcinoma (18 papers, 2012 to 2025). Carcinoma, predominantly squamous cell, arising from the epithelial cells of the hypopharynx. "The present study compared several HPMA-based fluorescent probes for EGFR-specific labeling of hypopharyngeal carcinoma cells (FaDu) and breast adenocarcinoma cells (MDA-MB-231)." (PMID 31906300, 2020). "The dual PI3K/mTOR inhibitor NVP-BEZ235 (BEZ) has been shown to enhance the radiosensitivity of SQ20B laryngeal and FaDu hypopharyngeal cancer cells, overexpressing epidermal growth factor receptor (EGFR)." (PMID 31581445, 2019). "EGFR is overexpressed in hypopharyngeal carcinoma, which constitutes approximately 5% of HNSCC." (PMID 36983174, 2023). "We also show that all three STAT3 inhibitors, with STA‐21 having the most profound effect, can effectively suppress the continuous production of cancer‐related molecules, IL6, TNF, RELA(p65), EGFR, BCL2 and STAT3, previously associated with hypopharyngeal cancer, caused by acidic bile." (PMID 34850540, 2022). "The activation status of the PI3K/AKT/mTOR pathway was investigated in our series of 93 laryngeal and hypopharyngeal carcinomas by analyzing the immunohistochemical expression of multiple upstream and downstream components, such as EGFR, PDK1, PTEN, p-AKT and p-S6." (PMID 27119232, 2016). "EGFR-targeted CAR T-cells enhanced cytokine secretion and cytolysis in EGFR-positive hypopharyngeal carcinoma models." (PMID 40940995, 2025).
myocardial infarction (18 papers, 2013 to 2025). Gross necrosis of the myocardium, as a result of interruption of the blood supply to the area, as in coronary thrombosis. "This patient, who died from a myocardial infarction more than 5 years after diagnosis, represents the case of a good synergy between molecular profile of disease and reintroduction of an anti-EGFR with intermittent strategy." (PMID 38638862, 2024). "Activated RELA/p65 results in myocardial infarction, and activation of EGFR-dependent pathway strengthens cardiac fibrosis and exacerbates cardiac dysfunction in myocardial infarction." (PMID 36248430, 2022). "When comparing healthy hearts with hearts representing acute myocardial infarction, significant downregulation of EGFR, ERBB2, ERBB3, as well as EPHA2, was discovered in the infarcted heart, ERBB2 demonstrating the greatest difference in expression." (PMID 30342492, 2018). "Analysis of RTK expression in the acute myocardial infarction samples revealed 4 RTKs with significantly reduced expression (EGFR, ERBB2, ERBB3 and EPHA2) when compared to healthy heart." (PMID 30342492, 2018). "TMVR-group showed more clinical sickness with more previous AMI (acute myocardial infarction) (P-value 0.023), with more coronary pathology (P-value 0.001), worse renal function (creatinine & EGFR, P-value 0.001), and worse lung capacity (COPD with P-value 0.001)." (PMID 41058678, 2025). "In EGFR(-) group, factors selected were age, gender, myocardial infarction, cerebrovascular disease, chronic pulmonary disease, number of lymph node examined, tumor stage, surgical intervention, radiotherapy, ECOG performance status, malignant pleural effusion, and a history of smoking." (PMID 31419239, 2019). "Stimulation of EGFR/ErbB receptors by amphiregulin (AR), another member of EGF family of ligands, induced cardiac fibrosis after myocardial infarction highlighting the detrimental role of EGFR/ErbBs in cardiac pathology." (PMID 34408653, 2021). "While EGFR TKIs are generally well tolerated, cardiotoxicities (including QT interval prolongation, left ventricular ejection fraction (LVEF) reduction, myocardial infarction (MI), atrial fibrillation (AF), and heart failure (HF)) have been reported for some TKIs." (PMID 40346640, 2025). "One patient developed an acute myocardial infarction but recovered with appropriate treatment (including percutaneous coronary intervention); this event was considered unlikely to be related to retreatment with EGFR-TKIs." (PMID 40704256, 2025). "Importantly, EGFR targeting therapies have not been tested in clinical trials in humans diagnosed with myocardial infarction." (PMID 34404849, 2021).
non-Hodgkin lymphoma (18 papers, 2007 to 2026). Distinct from Hodgkin lymphoma both morphologically and biologically, non-Hodgkin lymphoma (NHL) is characterized by the absence of Reed-Sternberg cells, can occur at any age, and usually presents as a localized or generalized lymphadenopathy associated with fever and weight loss. "Navitoclax has been applied to boost the treatment and basic science of chronic lymphoid leukemia, hematological malignancies, non-Hodgkin's lymphoma, solid tumors, and EGFR activating mutation." (PMID 33737523, 2021). "Wattenberg and colleagues recently reported that radiation exposure increased cell surface and total protein expression of HER2, EGFR, and CD20 in breast cancer, HNSCC, and non-Hodgkin lymphoma (NHL) cell lines, respectively." (PMID 28698765, 2017). "EGFR-CAR NK-92 cells can usually recognize and attack target cells in several hours, but they can survive only several days because they have to be irradiated as the cell line was originally established from a patient with non-Hodgkin's lymphoma." (PMID 27050072, 2016). "We have previously identified BCL-XL upregulation as a main effector in preventing RAS mutant CRC cell lines from anti-EGFR antibody induced apoptosis, and in CD20-positive B-cell Non-Hodgkin Lymphoma (B-NHL) cells from rituximab-induced apoptosis." (PMID 28507280, 2017). "Antigen-specific monoclonal antibodies (mAbs) are established as immunotherapeutic agents for the treatment of human malignancies such as non-Hodgkin lymphoma (NHL), CD30-positive lymphoma, EGFR-expressing advanced bowel cancer, metastatic colorectal carcinoma." (PMID 25496493, 2014).
Thrombocytopenia (18 papers, 2008 to 2026). A reduction in the number of circulating thrombocytes. "For leukopenia and thrombocytopenia, Osimertinib showed the highest incidence rates among EGFR-TKIs at 8% and 9%, respectively, but these were still much lower than the chemotherapy group’s 29% and 19%." (PMID 40135231, 2025). "The model was based on eight objectively measured and readily available variables: modified WHO functional class, 6MWD, PVR, EGFR, thrombocytopenia, mild ILD, NT-proBNP/BNP, and Dbil." (PMID 37689662, 2023). "Compared with chemotherapy, EGFR-TKIs led to more grade 3–4 rash, but less fatigue/asthenia disorder, leukopenia and thrombocytopenia." (PMID 25029199, 2014). "Regarding grade 3–4 toxicity data, our analysis demonstrated that although EGFR-TKIs produced more rash, they produced less fatigue/asthenia disorder, leukopenia and thrombocytopenia than second-line chemotherapy." (PMID 25029199, 2014). "Due to thrombocytopenia, chemotherapy had to be stopped early and was replaced by the EGFR inhibitor cetuximab." (PMID 18226196, 2008). "Notably, our model development approach took into account the multisystem clinical manifestations in patients with SLE, including EGFR, thrombocytopenia, and mild ILD." (PMID 37689662, 2023). "The occurrence rates of thrombocytopenia for VEGF and EGFR inhibitors were 25% (95% CI: 14%, 36%) and 18% (95% CI: 12%, 23%)." (PMID 37324019, 2023).